MYC (MYC proto-oncogene, bHLH transcription factor)
Diseases named in the same sentence as MYC in open-access papers (continued):
Sharing a sentence is not in itself a finding about the gene and the disease.
tumor (continued). "All three MYC tumor clusters present a comparable expression of those genes among them, and a lower expression compared to their hypothesized cells of origin." (PMID 35318328, 2022). "Thus, MYC expression above the physiologically allowed threshold can induce tumor development or strongly accelerate tumorigenesis in multiple tissues." (PMID 35847359, 2022). "It regulates cell proliferation and differentiation through a variety of mechanisms, such as the regulation and amplification of target genes, so the study of MYC gene and its related products may have positive significance for tumor detection and treatment." (PMID 35305591, 2022). "Additionally, about 15% of SCLC tumors have MYC amplification, thereby providing additional oncogenic stresses during the tumor cell cycle." (PMID 35584676, 2022). "However, in the sporadic group, these MYC amplifications were present in both tumour compartments in only one case." (PMID 35159086, 2022). "Additionally, in luminal tumors, Erα induces MYC expression, which, in turn, participates as a cofactor of Erα, favoring tumor proliferation." (PMID 35053485, 2022). "However, ncRNAs regulate not only activation of immune cells, but also affect the infiltration of these cells into the tumour as they for example interfere with important signalling pathways such as Wnt/β-catenin or MYC signalling." (PMID 36358867, 2022). "The role of enhanced polyamine synthesis (ODC induction) in the prevention of tissue injury (e.g., cerebral IRI), the development of neoplasia (e.g., MYC amplified tumors), as well as developmental abnormalities (e.g., Bachmann–Bupp and Robinson–Snyder Syndromes) has been documented." (PMID 35893120, 2022). "Inhibition of apoptosis may thus emerge as a good strategy to counteract cancer progression in competitive contexts; of note, we recently found a positive correlation between cell death amount at the tumor/stroma interface and MYC levels in human cancers." (PMID 36704198, 2022). "We may postulate that the translocations that lead to high BCL-2 and high MYC expression in DHL may arise at the GC B cell stage but that, as evidenced by the RNA-seq analysis, the high expression of MYC/BCL-2 is what drives the tumour signature." (PMID 35961968, 2022). "However, of note was the down regulation of tumour invasiveness genes and the MYC oncogene signature indicated an anti-neoplastic AM630 activity in this context." (PMID 35408449, 2022). "Tumor xenograft in nude mice was carried out to study whether miR-34a-5p/c-MYC/DNMT3a axis regulates CRC in vivo." (PMID 34623601, 2022). "ssGSEA analysis showed that L1CAM positively connected with cellular response to hypoxia, tumor proliferation signature, DNA repair, G2M checkpoint, MYC targets, TGFB, IL-10 anti-inflammatory signaling pathway, DNA replication, collagen production, and ECM degradation." (PMID 36212450, 2022). "The relationship of BL to germinal center MYC translocations means that virtually any antigenic stimulus could promote tumor development." (PMID 35897021, 2022). "Restoring miR-34a-5p or depleting c-MYC in MSC-EV limited CRC tumor formation." (PMID 34623601, 2022). "Furthermore, other factors that participate in tumor-genesis, including c-MYC, metalloproteinase 7 (MMP-7), and the vascular endothelial growth factor (VEGF), are stimulated by the β-catenin/TCF-LEF complex." (PMID 37305016, 2022). "We observed a delay in MyC-CaP tumor growth with the combination of RT + PIC." (PMID 35999216, 2022). "In addition, MYC maintains the tumor microenvironment by instructing tissue remodeling, angiogenesis, and inflammation, even when it is not overexpressed." (PMID 36860495, 2022). "Most patients had high expression of MYC protein in the preBAT tumor sample." (PMID 36194476, 2022).
tumor (continued). "However, our study revealed that OSA-related chronic intermittent hypoxia accelerates tumor cell proliferation, possibly by involving MYC pathways." (PMID 35805134, 2022). "For example, knockdown of the lncRNA LINRIS in colorectal cancer blocks K139 ubiquitination of IGF2BP2 (a m6A reader), preventing its degradation by the autophagic lysosomal pathway and ultimately, attenuating the downstream pathways of IGF2BP2, such as MYC-mediated glycolysis in tumor cells." (PMID 35794625, 2022). "Moreover, PTPN2 is a pro-tumor gene in MYC-driven B-cell lymphoma, and contributes to tumor proliferation by promoting G1 to S phase transition of the cell cycle." (PMID 36077422, 2022). "About 11% of the patients in our cohort harbored MYC CNVs, which may be a candidate for tumor genesis and progression." (PMID 35785159, 2022). "Interestingly, it was reported that a decrease in the expression of miR-7 carried out by c-MYC resulted in an overexpression of Fas-L in M1 macrophages, thus promoting greater apoptosis in tumor stromal macrophages (tumor stromal macrophages)." (PMID 36012357, 2022). "Our results suggest that directly targeting the TCA cycle, rather than glutamine catabolism, may be a promising therapeutic approach for MYC-driven tumours." (PMID 35945217, 2022). "Interestingly, GATA3-positive tumours had higher levels of c-MYC and proliferation gene signatures than other PTCLs." (PMID 35681778, 2022). "As a oncogene, MYC can regulates tumor DNA repair, growth, metabolism and apoptosis." (PMID 36249057, 2022). "In cancer cells addicted to their aberrant MYC function, suppression can lead to apoptosis, with minimal effects on non-addicted, non-oncogenic cells, providing a wide therapeutic window for specific and efficacious anti-tumor treatment." (PMID 36613820, 2022). "In addition, LUSC carrying high UPR was accompanied by an aggressive phenotype in LUSC, as indicated by the enormously positive correlation with MYC targets, DNA repair, tumor proliferation, and hypoxia signatures." (PMID 36291782, 2022). "The results demonstrated that ATG5 expression was significantly positively correlated with tumor proliferation signatures, MYC targets, DNA repair, DNA replication, and G2M checkpoint in HNSCC (p < 0.05), and the Spearman coefficients were 0.38, 0.28, 0.25, 0.34, and 0.41, respectively." (PMID 36185455, 2022). "For example, SRSF1 regulates the alternative splicing of the tumor suppressor BIN1, which interacts with the proto-oncogene MYC to inhibit its proliferative activity, while SRSF1 overexpression endorses BIN1 exon12a inclusion that lacks tumor-suppressor activity due to reduced binding with MYC." (PMID 35027535, 2022). "Clearly, MYC was the most frequently changed gene across many tumour types, followed by MGA." (PMID 35801728, 2022). "We suggest that in tumor cells with IGH/MYC translocation, this task may be tackled by affecting the activity of IGH locus enhancers." (PMID 35563017, 2022). "Of note, the ASO-mediated inhibition of MYC eRNA expression may be superior compared to an alternative strategy, in which BRD4 inhibitors also suppressed tumor cell-associated MYC expression." (PMID 35039581, 2022). "Taken together, miR-138 may have a strong tumor-suppressive effect in CRC by targeting several transcripts involved in cell cycle progression either directly or indirectly via MYC." (PMID 34937878, 2022).
tumor (continued). "A very interesting question is whether and how and the intra-tumor heterogeneous expression of MYC contributes to MB progression and relapse." (PMID 36340043, 2022). "Upregulated MYC leads to the subsequent glycolysis improvement and tumor cell proliferation." (PMID 35351856, 2022). "Previous study demonstrated that MYC oncogene was associated the suppression in tumour immunity, which suggest that the downregulation of MYC oncogenic pathway may contribute shaping the immune-depleted tumour microenvironment of CS2." (PMID 36159794, 2022). "Interestingly, the least responding tumours to neoadjuvant therapy presented an elevated MYC signature and earlier disease recurrence compared to the most responding tumours." (PMID 35267409, 2022). "This dominant pro-tumor activity makes MYC an attractive target for cancer therapy." (PMID 36018850, 2022). "Moreover, in approximately 50% of cancers especially those fueled by MYC, Hsp90 acts as a nucleating site to form functionally integrated complexes termed ‘epichaperome’, which render tumor cells more sensitive to Hsp90 inhibitors (Hsp90i)." (PMID 36341371, 2022). "It is possible that the tumor suppression by BRCA1 may be in part mediated by ZNF148 activation as a result of MYC downregulation." (PMID 36207293, 2022). "Together, these findings show the relevance of IFN signaling in suppressing tumor growth in TNBCs and underscore the critical role of MYC in suppressing the IFN response via direct inhibition of immunomodulatory factors downstream and in parallel of cGAS/STING signaling." (PMID 36323660, 2022). "MYC is undoubtedly the master regulator of the tumor microenvironment." (PMID 36139534, 2022). "Notably, tumor-related signaling pathways such as PI3K, MYC, mTOR, and Wnt were significantly enriched in high-risk group, and continuous activation of these pathways have been demonstrated to be linked with HCC." (PMID 35711939, 2022). "In conclusion, our research indicates that MYC might play a central role in the anit-tumor mechanisms of eucalyptol." (PMID 36331666, 2022). "In addition, the combination of OTX015 and panobinostat significantly inhibited tumor growth in MYC-amplified MB xenografted mice by downregulating expression of MYC, compared to single-agent therapy." (PMID 36357906, 2022). "Activation of these ISR regulators may also occur in response to oncogenic drivers, such as MYC amplification and loss of the PTEN tumor suppressor, frequently observed in prostate tumors." (PMID 36107759, 2022). "However, in vivo experiments with these compounds had limitations, namely the rapid metabolism of 10074-G5 to inactive metabolites resulted in tumor concentrations of 10074-G5 insufficient to inhibit c-MYC/MAX dimerization." (PMID 36551697, 2022). "Importantly, MEN1 depletion induced inhibition of activity of MYC proto-oncogene, known to be amplified in around 64% of OC tumours and activated in over half of human cancers including OC." (PMID 36333801, 2022). "In addition to the interference with a key tumor suppressor, we overexpressed the proto-oncogene c-MYC in primary malignant B cells from CLL patients." (PMID 36266281, 2022). "Moreover, GSVA revealed significantly differentially expressed pathways in paired pRCC samples, and those with Hallmarks of “MYC/E2F targets,” “G2M checkpoints,” and “DNA repair” stood out as highly expressed ones in tumor tissues." (PMID 35502201, 2022). "A recent study revealed that MYC inhibitor not only suppressed tumor growth in mice, but also increased T cell immune infiltration, enhanced PD-L1 expression on tumors, and increased tumor sensitivity to anti-PD1 immunotherapy." (PMID 36505846, 2022).
tumor (continued). "The finding that miR-3189-3p reduces levels of c-MYC protein under stress is significant since upregulation of this oncogene is an important step in the survival response of tumor cells under nutrient deprivation or other types of stresses in the tumor microenvironment." (PMID 35642054, 2022). "These discrepancies might be explained by the presence of several determinants, both intrinsic (e.g. mutational co-dependencies, metabolic plasticity) or environmental (e.g. tumor microenvironment), that can influence MYC-related prognosis in MB patients." (PMID 36340043, 2022). "FISH assays for MYC/BCL2/BCL6 in tumor tissues were performed in 11 (65%) patients." (PMID 36483984, 2022). "This suggested that NCAPG2 might play a pro-tumor role through the mTORC1 signaling pathway, DNA repair, and MYC targets." (PMID 36139554, 2022). "Given that MYC is a recognized proangiogenic factor and that angiogenesis is a key aspect in tumor growth, survival, and metastasis, we analyzed the capacity of MDA-MB-231 cells to induce angiogenesis after 3 days of Omomyc expression and compared it with that of untreated or GFP-expressing cells." (PMID 36860495, 2022). "While MYC overexpression reduces response to anti-PD-L1, MYC inactivation in combination with anti-PD-L1 delayed tumor recurrence and extended survival in mice, suggesting that MYC expression enhances tumor immune evasion and reduces efficacy of PD-1 blockade as a monotherapy." (PMID 35760778, 2022). "Interestingly, when directly comparing SHH versus MYC tumor cells via DE analysis, we found some of these mid/hindbrain and PGCs predictor genes as significantly upregulated in the respective subgroups." (PMID 35318328, 2022). "Tumours over expressing MYC have been previously identified as good targets for CHK1 inhibitors." (PMID 36240065, 2022). "The MYC stem gene is activated after Lgr5+ destroys colorectal cancer stem cells in the tumour." (PMID 35563449, 2022). "Nonetheless, these data suggest that at least in a subset of primary PCa, increased expression of KMT2A may contribute to tumor development, and that its expression in relationship to MYC activity modulates cancer progression." (PMID 36181613, 2022). "We tested whether CPI-613 could elicit tumour suppression in vivo in a MYC-driven B-cell lymphoma model initiated by subcutaneous injection of RAJI cells into mice." (PMID 35945217, 2022). "However, since our MYC_BC signature was derived from MYC-driven breast tumor models, we anticipated that it would provide additional insight into MYC-driven tumor-immune alterations relevant to TNBC." (PMID 35760778, 2022). "This indicates that HDAC3 may have a more general tumor-suppressive role in keeping c-MYC target genes at bay." (PMID 36846090, 2022). "Importantly, MYC-overexpressing cancer cells show an “oncogene addiction” to MYC, which implies that targeted inactivation leads to tumor regression." (PMID 36611833, 2022). "Notably, only patients with preBAT ARAMW scores greater than 0.6 exhibited a significant decrease in MYC protein expression, supporting the concept that high preBAT AR activity is required for downregulation of MYC and tumor regression by SPA." (PMID 36194476, 2022). "Likewise, prostate-specific deletion of Tubb4a reduces spontaneous tumor growth and metastasis via inhibition of NF-κB, cyclin D1, and c-MYC signaling activation." (PMID 35589707, 2022). "MYC, a prominent oncogene and transcription factor, is also expressed primarily in TACs, plays an essential role in early embryonic development, and acts as a protooncogene in tumor cells." (PMID 35015732, 2022). "Also, Kortlever and coworkers showed in an in vivo adenocarcinoma model that stromal changes and tumor regression, which appeared after the deactivation of MYC, were mediated by NK cells." (PMID 36361720, 2022).
tumor (continued). "MYC was also shown to regulate purine biosynthesis and ribosome biogenesis in SCLC68,69, however, the associated KEGG pathways were similarly enriched in both tumor subtypes." (PMID 35440132, 2022). "A differential 5hmC gene body analysis between disease states identified genes in proliferative pathways to have a progressive increase in 5hmC levels during tumor progression, which was also observed for oncogenic pathways, such as MYC targets and E2F targets." (PMID 36251389, 2022). "MYC ChIP-seq peaks that occurred in tumors and/or organoids overlapped with 59 IFN signaling pathway-associated genes that were repressed by MYC in the tumors, sorted tumor epithelial cells and/or organoids." (PMID 36323660, 2022). "This is in contrast to the defined tumor nodules developed in our MYC-induced mouse models." (PMID 35053588, 2022). "However, DDX5 is a highly active G4-resolvase that can effectively unfold the G4 structure and thus promote the transcription of the MYC gene to promote tumorigenesis and tumor progression." (PMID 35992805, 2022). "The MYC inhibitor 361 (MYCi361) suppressed the tumor growth of MycCaP PC cell lines in mice, increased the tumor immune cell infiltration, upregulated PD-L1 on tumor cells, and sensitized cancer to anti-PD-1 immunotherapy." (PMID 35203446, 2022). "In addition, the anti-tumor effect of MSC-EV-derived miR-34a-5p was reversed by c-MYC overexpression." (PMID 34623601, 2022). "In addition, PD-L1 expression was upregulated on tumor cells by signaling through ASPH-Notch-MYC in both murine TNBC and HCC animal models." (PMID 35392977, 2022). "Similarly, in patients, high pretreatment AR activity predicts the downregulation of MYC, tumor regression, and both progression-free and overall survival on BAT." (PMID 36194476, 2022). "This tumor-suppressive role of miR-769-3p may be derived from immune-related gene signature activation or c-MYC oncogene pathway suppression." (PMID 36139534, 2022). "All cases of high grade DLBCL with karyotype and FISH ascertained during 2005–2020 (31 MYC+: 13 bone marrow, seven lymph nodes, nine other tumor site; 28 MYC−: eight bone marrow, 11 lymph nodes, eight other tumor site, tumor site not available for three cases) were included in the study." (PMID 36051032, 2022). "MYC can also promote tumor proliferation in BC, and it may be a potential therapeutic target of triple-negative BC patients." (PMID 36672769, 2022). "Human CD44/MYC-high cancer cells tended to localize the outside of the primary tumor." (PMID 35611554, 2022). "MYC targets v1 signaling and might be related to the higher rates of cell proliferation, resulting in increased aggressiveness of the tumor and worse survival." (PMID 35807355, 2022). "Small-molecule inhibitors or monoclonal antibodies of targeted therapy, such as inhibitors for epidermal growth factor receptor (EGFR), transforming growth factor (TGF)-β, BRAF, VEGF, and MYC, can produce impressive tumor responses in selected patients while having potentially fewer side effects." (PMID 36119019, 2022). "In this study, we were able to detect a strong association between MYC levels and tumorigenesis despite the area of the colon from which the tumor was resected, arguing that MYC may be a critical factor in tumorigenesis." (PMID 36139061, 2022).